PTTG1 (PTTG1 regulator of sister chromatid separation, securin)
Diseases named in the same sentence as PTTG1 in open-access papers (continued):
Sharing a sentence is not in itself a finding about the gene and the disease.
myeloid leukemia (1 paper, 2018). A clonal proliferation of myeloid cells and their precursors in the bone marrow, peripheral blood, and spleen. "In this study, we aim to investigate the anti-cancer effects of luteolin on cells with differential PTTG1 expression and their underlying mechanisms in human myeloid leukemia cells." (PMID 29649138, 2018). "In the present study, we aim to investigate the effects of PTTG1 expression on luteolin-mediated anti-cancer activity and their underlying mechanisms in human myeloid leukemia cells." (PMID 29649138, 2018). "Luteolin displayed a stronger apoptosis on undifferentiated myeloid leukemia cells with higher PTTG1 expression levels than on PMA- or ATRA-differentiated cells with lower PTTG1 expression levels." (PMID 29649138, 2018). "Here, we provide the first evidence that the anti-cancer effects of luteolin are modulated by PTTG1 levels in human myeloid leukemia cells." (PMID 29649138, 2018). "To investigate the cytotoxic effect of luteolin in myeloid leukemia cells with differential PTTG1 expression, we first determined the PTTG1 protein level in PMA- and ATRA-differentiated THP-1 cells." (PMID 29649138, 2018). "Our findings indicated that PTTG1 overexpression triggers the expression of several genes promoting cell proliferation and cell-cycle progression in human myeloid leukemia cells." (PMID 29649138, 2018). "PTTG1 oncoprotein overexpression may modulate cell proliferation-related regulators and enhance the response of myeloid leukemia cells to luteolin." (PMID 29649138, 2018). "High expression levels of PTTG1 may enhance the response of myeloid leukemia cells to luteolin, which may be beneficial for the anti-leukemic effects of luteolin." (PMID 29649138, 2018). "Whether high levels of PTTG1 expression directly affects these cell-proliferative regulators to sensitize the apoptotic response to luteolin in human myeloid leukemia cells remains unknown and needs to be further investigated." (PMID 29649138, 2018). "Our current findings revealed that PTTG1 overexpression may enhance the effectiveness of luteolin by regulating the molecules involved in cell proliferation and cell-cycle progression in human myeloid leukemia cells." (PMID 29649138, 2018). "PTTG1 knockdown decreased the cleavage of both caspase 3 and PARP1, which indicated that PTTG1 expression levels modulated the apoptotic effect induced by luteolin in human myeloid leukemia cells." (PMID 29649138, 2018).
oral cancer (1 paper, 2021).
pharynx tumors (1 paper, 2020). "Moreover, the highest upregulation of PTTG3P expression was observed in pharynx tumors compared to oral and larynx locations, and instances of PTTG1 and PTTG2 were significantly upregulated in HNSCC tumor tissues compared with normal samples." (PMID 32824814, 2020).
preeclampsia (1 paper, 2016). Preeclampsia is a hypertensive disorder of pregnancy that is characterized by new-onset hypertension with proteinuria presenting after 20 weeks of gestation, and depending on mild or severe forms may initially present with severe headache, visual disturbances, and hyperreflexia. "Furthermore, PTTG1 was highly expressed in second trimester preeclampsia compared with normal-term placenta and third trimester preeclampsia (data not shown)." (PMID 26900962, 2016).
Stroke (1 paper, 2025). Sudden impairment of blood flow to a part of the brain due to occlusion or rupture of an artery to the brain. "Likewise, we found PTTG1 as a regulator of downregulated target genes of both the neuronal classes, which has been found to be dysregulated in a model of stroke and fetal alcohol syndrome." (PMID 41282152, 2025).
T-cell leukemia (1 paper, 2022). A malignant disease of the T-lymphocytes in the bone marrow, thymus, and/or blood. "A previous study reported that higher PTTG1 expression could be found in the CD4+ and CD8+ T lymphocytes of adult T-cell leukemia patients than that of healthy subjects, which implied an intimate association between PTTG1 and lymphocytes." (PMID 35768832, 2022).
testicular cancer (1 paper, 2021). A primary or metastatic malignant neoplasm that affects the testis. "Previously, we analyzed PTTG1 localization in a subset of human testicular cancers." (PMID 33430117, 2021). "The exact biological effects of PTTG1 on testis cancer carcinogenesis and progression remain unclear and its functional role has not yet been fully explored." (PMID 33430117, 2021). "Immunostaining analysis revealed that in in situ testicular cancer (CIS), PTTG1 showed nuclear staining only in isolated cells." (PMID 33430117, 2021).
testicular seminoma (1 paper, 2026). A malignant germ cell tumor arising from the testis. "Our previous in vitro studies demonstrated that PTTG1 nuclear expression promotes invasiveness, dedifferentiation, and neolymphangiogenesis in testicular seminoma." (PMID 41976385, 2026).
Thrombocytopenia (1 paper, 2025). A reduction in the number of circulating thrombocytes. "Additionally, Pttg1-null mice exhibited testicular and splenic hypoplasia, thymic hyperplasia, and thrombocytopenia 47, indicating that securin maintains global chromosomal stability and cell cycle progression during embryonic and postnatal development." (PMID 41323790, 2025).
thymic carcinoma (1 paper, 2017). Thymic carcinoma (TC) is a type of thymic epithelial neoplasm characterized by a high malignant potential. "We previously demonstrated that the CDK inhibitor PHA848125 - shown to possess a safety profile and a promising activity against thymic carcinoma in a phase I clinical study - inhibited proliferation of A375 cells, at least in part, through down-regulation of PTTG1." (PMID 29371923, 2017).
Wilms tumor (1 paper, 2023). An embryonal neoplasm characterized by the presence of epithelial, mesenchymal, and blastema components. "Overall, our findings highlight the critical role of Smarca4 in kidney development and the regulation of Pttg1 expression, providing new insights into the mechanisms underlying nephron tubule formation and renal disease, including Wilms tumor." (PMID 37727504, 2023).
tumor (166 papers, 2005 to 2026). "Future research should also investigate the functional impact of these PTTG1 variants on protein expression and cellular phenotypes in PitNET to better elucidate potential causal links between genetic variation and tumor behavior." (PMID 41573212, 2025). "Increased PTTG1 expression is associated with higher tumor proliferation and aggressiveness across multiple tumor types." (PMID 41573212, 2025). "The roles of RAC2 and PTTG1 are critical in the molecular pathways underlying cancer biology, with both molecules contributing significantly to tumor initiation, progression, metastasis, and resistance to therapies." (PMID 40072059, 2025). "Overexpression of PTTG1 promotes tumor growth, but the impact of its genetic variants in PitNETs size is insufficiently defined." (PMID 41573212, 2025). "Our study confirmed elevated PTTG1 expression in LUAD tumor tissues and its association with worse OS." (PMID 41312363, 2025). "In nearly a dozen tumor entities, an overexpression of PTTG1 is associated with a poor overall survival, and in PitNET, a correlation with higher invasiveness has been confirmed." (PMID 39548496, 2024). "PTTG1 is overexpressed in many tumor types, predicts poor prognosis, and is associated with therapies." (PMID 37243239, 2023). "PTTG1 is a tumour transforming gene, which can cause cell transformation without the participation of any auxiliary gene, and is closely related to the occurrence of many tumours." (PMID 35037540, 2022). "This means that the overexpression of PTTG1 is linked to high infiltration of immune cells and stromal cells but low tumor purity in these tumors." (PMID 35281830, 2022). "PTTG1 is also involved in mitosis and linked to tumor formation, prognosis, and cancer treatment in various tumors." (PMID 35281830, 2022). "The aim of this study was to perform a preliminary analysis of PTTG1 expression, mutational information, prognostic value and potential tumor regulatory mechanisms by integrating tumor genome data from multiple public databases." (PMID 35281830, 2022). "We also found that the mRNA levels PTTG1were positively associated the tumor grade, which is supported by patients with severe tumor grade have high mRNA levels of PTTG1." (PMID 32272902, 2020). "The high level of PTTG1 is commonly associated with an enhanced proliferative capacity, increased tumor grade and high invasive potential." (PMID 32793179, 2020). "Mechanistically, PTTG1 has been shown to induce cellular transformation, promotes tumorigenesis, enhances tumor-associated angiogenesis." (PMID 30853662, 2019). "In malignant tumors, previous data demonstrated the association between PTTG1 levels, tumor angiogenesis and metastasis." (PMID 31572301, 2019). "The high level of PTTG1 is commonly associated with an enhanced proliferative capacity, increased tumour grade and high invasive potential." (PMID 30822312, 2019). "A high Ki-67 and TUNEL labeling indices and increased phosphorylated AKT (serine/threonine-specific protein kinase), phosphorylated MAPK (p44/42 MAPK), and PTTG1 (pituitary tumor-transforming 1) immunostaining were associated with early tumor recurrence." (PMID 30020466, 2019). "The pituitary tumor transforming gene 1 (PTTG1) is implicated in tumor growth, metastasis and drug resistance." (PMID 29371923, 2017). "PTTG1 promotes tumor angiogenesis, but mechanisms underlying PTTG1-mediated angiogenesis, cell death and drug responses in vivo are unclear." (PMID 21858218, 2011). "PTTG1 has been identified as one of eight signature genes upregulated in human primary tumors that are associated with tumor metastasis." (PMID 19014669, 2008).
tumor (continued). "In fact, PTTG1 over-expression has been associated with aneuploidy generation, what correlates with a differentiated prognosis in multiple tumor types." (PMID 18426563, 2008). "Further, several other studies implicate that PTTG-1 overexpression was associated to chromosomal instability, increased distant metastases, increased neoangiogenesis and invasiveness of the tumor." (PMID 16426442, 2006). "Importantly, Cox regression models revealed that risk scores based on the expression of CDC20, KIF20A and PTTG1 were independent prognostic variables than indices of tumor grade or IDH‐mutant status." (PMID 40047299, 2025). "Similarly, in PitNETs, PTTG1 and Ki-67 expression are strongly correlated, and higher levels of both markers are linked to increased recurrence risk and more aggressive tumor behavior." (PMID 41573212, 2025). "In contrast, PTTG1 acts as a regulator of sister chromatid separation during cell division under physiological conditions, which is closely linked to genetic instability, aneuploidy, tumor progression, invasion, and metastasis." (PMID 40407808, 2025). "Also included is the human securin gene PTTG1, which was initially identified as an oncogene in malignant pituitary tumors but has been associated with tumor aggressiveness and invasiveness in various other cancer entities." (PMID 39548496, 2024). "Besides, PTTG1 has been implicated in processes such as tumor induction, progression, and metastasis." (PMID 35805898, 2022). "The PTTG1 is linked to many tumors and various of pathways which could be the potential mechanism for tumor formation." (PMID 35281830, 2022). "Therefore, in the current study, we attempted to devise a multi-epitope-based vaccine via bioinformatics tools targeting the major tumor-associated antigens including SP17, AKAP4, and PTTG1, which have been implicated in in tumor proliferation and invasion." (PMID 35463817, 2022). "In addition, PTTG1 is substantially connected with tumor invasiveness and is known to be a crucial gene associated with tumor metastasis, whose expression levels in normal human tissue are low." (PMID 35768832, 2022). "Additionally, PTTG1 is related to immune infiltration, immune checkpoints, tumor mutational burden, and microsatellite instability." (PMID 35281830, 2022). "Thus, we explored the association between the candidate genes and tumour infiltrating immune cells and investigate the potential ability of PTTG1 expression in predicting ICB response in pRCC patients." (PMID 35037540, 2022). "However, PTTG1 is highly correlated with tumor invasiveness and is known as a critical gene associated with tumor metastasis, although its expression in normal human tissue is rare." (PMID 33498448, 2021). "Interestingly, we found the mRNA levels of PTTG1 are associated with lymphatic metastasis, tumor grade, and survival rates." (PMID 32272902, 2020). "PTTG1 has been identified as a critical signature gene associated with tumor metastasis." (PMID 33304656, 2020). "On the contrary, with the increasing tumor size, this subgroup of nuclear PTTG1-positive cells move from the center to the periphery of the tumor, and it might be associated with neoplastic infiltration of surrounding tissue." (PMID 31572301, 2019). "Moreover, high expression of PTTG1 is associated with greatly aggressive tumor and with the onset of metastasis." (PMID 31572301, 2019). "Furthermore, high levels of PTTG1 were found to promote resistance to gefitinib-induced apoptosis in various tumor cell lines and to be associated with saracatinib resistance in ovarian cancer cells." (PMID 29371923, 2017). "PTTG1 has been identified as a key signature gene associated with tumor metastasis." (PMID 26264222, 2015). "We also evaluated the possibility that loss of heterozygosity (LOH) events involving the PTTG1 locus could also explain the higher amount of protein present in different tumor biopsies and tumor cell lines." (PMID 18426563, 2008).
tumor (continued). "Hence, the MAPK pathway might also be a potential mechanism associated with PTTG1 and tumor formation." (PMID 35281830, 2022). "Furthermore, PTTG1 deficient mice demonstrated suppression of tumor growth and EMT." (PMID 29190924, 2017). "Notably, PTTG1 is over-expressed in a vast array of malignancies including pituitary, colorectal, thyroid and lung cancer, and high levels of PTTG1 are commonly associated with an enhanced proliferative capacity, increased tumour grade and high invasive potential." (PMID 26445238, 2015). "In vivo, xenograft tumor growth was significantly reduced in nude mice injected with si-PTTG1 cells compared with controls (n = 6 per group; p < 0.05)." (PMID 41645360, 2026). "This study is the first to validate, at the protein level, the significant overexpression of ASPH and PTTG1 in LUAD tumor tissues, which is consistent with previous findings based on single-cell transcriptomics and bioinformatic analyses." (PMID 41312363, 2025). "A novel prognostic risk model based on four CRGs (ORC1, PTTG1, DLAT, PDHB) was developed to stratify COAD patients into high-risk and low-risk groups, assessing overall survival, tumor microenvironment, and mutational landscape differences." (PMID 40276654, 2025). "The dysregulation of PTTG1 amplifies the proliferation, invasion, and metastasis of tumor cells while concurrently suppressing apoptosis." (PMID 40877987, 2025). "The other tumor group showed high activity of a gene known as PTTG1, which plays a role in cell division and DNA repair." (PMID 40407808, 2025). "PTTG1 is a potent oncogene that drives malignant tumor progression via diverse mechanisms, prompting numerous investigations into the metastases associated with its overexpression." (PMID 39792809, 2025). "The significance of PTTG1 overexpression in tumor development, as emphasized in previous studies, was further underscored by our recent findings, with the present study elucidating the role of PTTG1 in OSCC metastasis." (PMID 39792809, 2025). "First, while our in vitro assays provide initial functional support, the study lacks in vivo validation using animal models, which is essential to confirm the roles of ASPH and PTTG1 in a physiological tumor microenvironment." (PMID 41312363, 2025). "This review highlights the molecular mechanisms by which RAC2 and PTTG1 influence tumorigenesis and describes their potential and efficacy as prognostic biomarkers and therapeutic targets in managing various neoplasms." (PMID 40072059, 2025). "Western blot analysis revealed that the protein expression levels of ASPH and PTTG1 were significantly higher in tumor tissues compared to adjacent normal tissues across all six paired LUAD samples (P < 0.001)." (PMID 41312363, 2025). "The observed differential expression of PTTG1 in tumors compared to adjacent non-tumor tissues supports its oncogenic role in HCC." (PMID 40315269, 2025). "A recent study has identified that PTTG1 upregulates the expression of particular immune checkpoint genes, facilitating tumor cells to evade immune surveillance." (PMID 40072059, 2025). "PTTG1 is also involved in HCC development, and overexpression of PTTG1 was correlated with more advanced tumor size, tumor grade, and TNM stage, and ultimately, poor prognosis." (PMID 40072059, 2025). "The results showed significantly higher expression of PTTG1 in tumor tissues compared to adjacent tissues (p < 0.05)." (PMID 40315269, 2025). "Thyroid hormone receptors (TRs) exert tumor-suppressive effects by inhibiting the expression of PTTG1 and the transcription factor Sp1, emphasizing the critical role of the TR-Sp1-PTTG1 signaling axis in HCC progression." (PMID 40315269, 2025). "The results demonstrated a significant decrease in cell proliferation and colony formation ability in the shRNA-PTTG1 group compared to the shRNA-NC group, suggesting an important role of PTTG1 in tumor proliferation." (PMID 38887516, 2024).